YAP1 (Yes1 associated transcriptional regulator)
Diseases named in the same sentence as YAP1 in open-access papers (continued):
Sharing a sentence is not in itself a finding about the gene and the disease.
lung cancer (continued). "Similarly, YAP1 activation is a mechanism of resistance to crizotinib therapy for ROS1-rearranged lung cancers." (PMID 34685695, 2021). "However, high mRNA levels of YAP1 were significantly correlated with a reduced OS in lung cancer (OS, HR = 1.4, p = 0.026)." (PMID 34150844, 2021). "YAP1 was activated when ALK-rearranged lung cancer cells were exposed to ALC." (PMID 31900393, 2020). "Monotherapy using YAP1 inhibitors may therefore have potential to suppress tumor growth in some ALK-rearranged lung cancers." (PMID 31900393, 2020). "Combinatorial therapy against ALK and YAP1 in the early stages of treatment may reduce the recurrence of ALK-positive lung cancer." (PMID 31900393, 2020). "In addition, β-Trcp regulates stability of the yes-associated protein 1 (YAP1) known as an oncogene in pancreatic cancer, and of Mxi1 that represses transcriptional activity of c-Myc in lung cancer through ubiquitination and proteasomal degradation." (PMID 32486158, 2020). "Yes Associated Protein 1 (YAP1) and WW Domain Containing Transcription Regulator 1 (WWTR1/TAZ) are key regulatory factors of Hippo Signaling pathways, and are targeted to develop effective lung cancer therapy by their inhibition." (PMID 31641374, 2019). "Results showed that the combination of IPA-3 plus auranofin abrogated the expression of total/phosphorylation of PAK1, PKCι, ERK 1/2, mTOR, AKT, and YAP1 in the 3 lung cancer cell lines studied HCC827 (EGFR-mutant LUAD), H23 (KRAS-mutant LUAD) and H520 (PAK1 overexpression)." (PMID 31660987, 2019). "In this study, we found ABCG2 and YAP1 were both overexpressed in lung cancer SP cells." (PMID 27911857, 2017). "In lung cancer, YAP1 overexpression has been correlated with a poor prognosis." (PMID 29179447, 2017). "Moreover, the YAP1 inhibitor verteporfin and YAP1 siRNA downregulated ABCG2 level through inhibition of YAP1 in lung cancer cells and sensitized them to the chemotherapy drug doxorubicin." (PMID 27911857, 2017). "We found co-localization of ABCG2 and the Hippo pathway effector YAP1 in lung carcinoma SP cells." (PMID 27911857, 2017). "In concordance with these observations, our data suggest that EGFR/KRAS driven signaling might activate YAP1 leading to its nuclear translocation in lung cancers." (PMID 26716514, 2016). "Furthermore, a study indicated that the expression of cytoplasmic YAP1, which is the inactive form, was associated with longer-progression free survival and overall survival in EGFR-TKI-treated lung cancer patients with EGFR mutations." (PMID 26716514, 2016). "Our study showed that total YAP1 was expressed in 75% and the active form of YAP1, nuclear YAP1 was expressed in 48% of primary lung cancer specimens which is in line with previous report that YAP1 was expressed in 66% of cases and is found to be present predominantly in nucleus." (PMID 26716514, 2016). "We have shown that YAP1 blockade could sensitize lung cancer cells to cisplatin, radiation and erlotinib." (PMID 26716514, 2016). "Our preliminary validation study indicated that YAP1 may be a bona fide mediator of cisplatin sensitivity in lung cancer cells." (PMID 26716514, 2016). "Finally, besides CRC, upregulated YAP1, cyclin D, CDK4/6, and DUB3 are similarly implicated in various cancers such as lung cancer and ovarian cancers, thus the implication of this axis in these malignancies should be investigated by further preclinical and clinical study." (PMID 39968498, 2025). "Recent studies have discovered molecular subtypes of SCNE lung cancer defined by ASCL1 (achaete-scute family bHLH transcription factor 1), NEUROD1 (neurogenic differentiation 1), POU2F3 (POU class 2 homeobox 3), and YAP1 (Yes1 associated transcriptional regulator) transcription factors." (PMID 37467967, 2023). "Furthermore, we identify YAP1 activation as a key cooperating event in RIT1-mutant lung cancer." (PMID 34373451, 2021). "In this study, we asked whether YAP1 regulates ABCG2 in lung cancer cells." (PMID 27911857, 2017).
lung cancer (continued). "Beyond the Hippo pathway, lung cancer cells survive EGFR inhibitor therapy through STAT3 and Src–YAP1 signaling activation." (PMID 40066231, 2025). "Of note, in the two PDX models we tested only one demonstrated YAP1/WWTR1/TEAD-dependent transcription in persister cells, highlighting that other mechanisms of persistence in EGFR mutant lung cancer must exist and need to be defined." (PMID 38658677, 2024). "In lung cancer, nicotine promotes migration and stemness of non-small cell lung adenocarcinoma (NSCLC) cells via the α7 nAChR/Yap1/E2F1 axis." (PMID 36284268, 2022). "Fascin-1 was found to activate PFKFB3 transcription through the YAP1/TEAD binding site in its promoter to further promote glycolysis in NSCLC cells, thereby promoting lung cancer cell metabolism and growth." (PMID 36033434, 2022). "Interestingly, we found that high expression levels of EGFR/MAP2K1/mTOR/TEAD1/YAP1 in lung cancer significantly decreased overall levels of active cytotoxic lymphocytes, mediated dysfunctional T-cell phenotypes, and produced worse overall survival rates of lung cancer cohorts." (PMID 35655775, 2022). "A recent lung cancer transcriptome meta-analysis showed that several HIPPO pathway component (NF2, LATS1, PTPN14, YAP1, TAZ, TAOK, and FAT1) genes were found to fuse in lung carcinoma, and they were independent prognosis factors for low lung cancer survival." (PMID 36147635, 2022). "In lung cancer, FSCN1 promotes cancer growth and metastasis by enhancing glycolysis and PFKFB3 expression through YAP1 activation." (PMID 35069968, 2021). "Here, we identified verteporfin, which is a known YAP1 inhibitor, as a striking therapeutic candidate for KRAS-mutant lung cancer cells involving the unresolved ER stress mechanisms." (PMID 33830081, 2021). "High levels of both miR-550a-3-5p and high metastatic lung cancer cell-derived exosomes markedly upregulated cleaved-PARP protein expression while downregulating pRB, CDK6, YAP1, CTGF, and CYR61 protein expression." (PMID 34530822, 2021). "We demonstrated that YAP1 was significantly activated both in vitro and in vivo when ALK-rearranged lung cancer cells were treated with ALC, and the combinatorial inhibition of YAP1 and ALK achieved the suppression of initial survival in vitro and in vivo." (PMID 31900393, 2020). "Combination therapy with VP and gefitinib inhibited YAP1, p-ERK and ps75-bad in lung cancer cells, and suppressed PC9 mir-630 knockout lung cancer xenografts in nude mice." (PMID 33178014, 2020). "Mechanistic characterization revealed that this drug combination abrogated expression and activation of membrane receptors and downstream signaling proteins crucial in lung cancer: EGFR, MET, PAK1, PKCι, ERK1/2, AKT, YAP1 and mTOR." (PMID 31660987, 2019). "In lung cancer, silencing or inhibition of ERK1/2 led to downregulation of YAP1 protein and YAP1 downstream genes." (PMID 31848326, 2019). "In lung cancer, YAP1 increases FGFR1 expression, and in cholangiocarcinoma, cross-talk between YAP1 and FGFR1, 2 and 4 has been shown." (PMID 30909436, 2019). "Our finding expands what is known about YAP1-promoted drug resistance through regulating a well-known ABC-transporter, ABCG2, in lung cancer." (PMID 27911857, 2017). "Disruption of YAP1 expression by siRNA attenuated the expression of ABCG2 transcript and significantly reduced the percentage of SP cells and sphere formation in lung cancer cells." (PMID 27911857, 2017). "Since cyclin D1 is present in the same chromosomal arm as YAP1 but in 11q13 and CCND1 is frequently amplified in lung cancer, we used one probe specific for cyclin D1 gene and another probe specific for YAP1 gene or FISH analyses." (PMID 24810989, 2014). "We quantified nuclear YAP1 and WWTR1 IHC expression in the panel of EGFR mutant lung cancer PDX." (PMID 38658677, 2024).
lung cancer (continued). "Interestingly, we found that lung cancer cohorts with genetic alterations of EGFR, MAP2K1, mTOR, TEAD1, and YAP1 exhibited worse prognoses of overall, disease-specific, and progression-free survival compared to patients with wild-type (WT) genes." (PMID 35655775, 2022). "Herein, we tested the directly physical interaction between ANKHD1 and YAP1, suggesting that ANKHD1 directly affects YAP1 transcriptional activity rather than triggers the Hippo pathway, which is consistent with a previous report in lung cancer." (PMID 35110552, 2022). "YAP1 upregulation was further identified as a mediator of resistance to combined TBK1 and MEK inhibition in KRAS mutant lung cancer cells and in a KRAS G12D mutant genetically engineered lung cancer mouse models." (PMID 34685695, 2021). "To investigate whether co-activation of YAP1 and RIT1 occurs in human lung cancer, we analyzed data from 230 human lung adenocarcinomas sequenced by The Cancer Genome Atlas6." (PMID 34373451, 2021). "A treatment targeting YAP1 and ALK has potential as an effective therapy for YAP1-dependent ALC-resistant ALK-rearranged lung cancer, and may reduce the regrowth of ALK-positive lung cancer." (PMID 31900393, 2020). "FGFR1 was also highly expressed in NSCLC and promoted tumor formation in lung cancer by interacting with SOX2, Hippo/YAP1 or Hedgehog pathway as our previously work reported 12, 13, 20, while deficiency of KLB did not influence the FGFR1 levels in cultured endothelial cells." (PMID 31695781, 2019). "Next, to verify the effects of YAP1 on NSCLC tumorigenesis and the EMT program in an in vivo model, we generated a luciferase-labeled stable YAP1 knockdown human lung cancer A549 cell line (Luc-shRNA-hYAP1-NEO) and a scrambled shRNA human lung cancer A549 cell line (Luc-shRNA-Scramble-NEO)." (PMID 29700328, 2018). "We also find that nicotine induces expression of Yap1 itself, and that the nicotine-mediated induction of Sox2 and Yap1 is not just specific to lung cancer cells but is also observed in human mesenchymal stem cells." (PMID 30322398, 2018). "Our study adds a new function for YAP1 that may be relevant to drug resistance and cancer therapy through regulation of ABCG2 and side population cell formation in lung cancer." (PMID 27911857, 2017). "We have recently shown that gefitinib or osimertinib treatment results in the activation of not only STAT3, but also Src-YAP1 signaling, potentially operating downstream of IL-6, to promote cell survival and limit the initial response to EGFR TKI treatment in EGFR mutant lung cancer." (PMID 28521301, 2017). "Taken together, our study is the first to indicate the potential role of YAP1 as a common modulator of resistance mechanisms and a potential novel, actionable target that can improve responses to platinum, radiation and EGFR-targeted therapy in lung cancer." (PMID 26716514, 2016). "Therefore, it is possible that like ES, in lung cancer, AURKA may stabilize YAP1 indirectly by phosphorylating NPM1." (PMID 39334449, 2024). "We focused on YAP1, as LINC02159 knockdown decreased its gene expression in NSCLC cells and a recent study suggested that ALYREF may regulate YAP1 5-methylcytosine modification to increase its mRNA stability in lung cancer." (PMID 37537569, 2023). "Studies have shown that YAP1 expression is induced by KRAS activation, aerobic glycolysis, GNAS, and the cancer upregulated gene (CUG) 2 exhibiting upregulated expression in lung cancer which could increase the expression of YAP1." (PMID 33648545, 2021).
lung cancer (continued). "Thus, our data suggests that YAP1 may be a common modulator of resistance mechanisms to platinum, radiation and EGFR-targeted therapies in lung cancer." (PMID 26716514, 2016). "YAP1 expression has been suggested as a negative prognostic factor for lung cancer survival." (PMID 26716514, 2016). "We exploited EKVX (lung cancer), CaSki (cervical cancer) and RO82 (thyroid cancer) cell lines harboring both genomic YAP1 amplification and YAP1 protein overexpression, in order to study the effects of downregulation of endogenous YAP1 by RNA-interference strategies." (PMID 24810989, 2014). "Additionally, YAP1 was identified as the target gene of exosomal miR-550a-3-5p, and miR-550a-3-5p may regulate the growth and migration of HBMECs by mediating YAP1, cleaved-PARP, pRB, CDK6, CTGF, and CYR61 protein expression, thus controlling brain metastasis of lung cancer." (PMID 34530822, 2021). "Most commercial laboratories offer limited or no testing for hereditary lung cancer variants, and no guideline has been established for the best way to manage unaffected carriers of variants associated with lung cancer, such as germline EGFR T790M, HER2 and YAP1 mutations." (PMID 32104210, 2020). "RB1 expression was mostly associated with a wild-type (wt) exon mutation status and its functionality in YAP1-positive cell lines was suggested by decreased or absent CDKN2A/2B expression, previously shown as an alternate mechanism to disable the RB1 pathway in lung cancer." (PMID 29088741, 2017). "Previous studies have proved that YAP1 promotes survival and dormancy without EGFR downstream signaling in EGFR-mutant lung cancer." (PMID 37215986, 2023). "However, the relationship between YAP1 and ABCG2 and YAP1 regulation of cancer cell side population in lung cancer have never been reported." (PMID 27911857, 2017).
pancreatic cancer (100 papers, 2012 to 2026). "Yes-associated protein 1 (YAP1), a transcriptional co-activator, has been recognised as a central node in the growth-promoting signalling pathways of pancreatic cancer." (PMID 42231052, 2026). "Functionally, we demonstrated that GPSM2 promotes colony formation and invasion of pancreatic cancer cells and was found to be mechanistically linked to the regulation of YAP1." (PMID 42231052, 2026). "Analysis of human clinical samples from the TCGA database shows that YAP1 is overexpressed in pancreatic cancer patients, and higher YAP1 expression is associated with lower overall survival rates." (PMID 39458993, 2024). "High expression levels of YAP1 were significantly associated with a variety of immune markers and immune cell subsets in pancreatic cancer." (PMID 34150844, 2021). "TCGC database showed that higher YAP1 expression is linked to a poorer prognosis in pancreatic cancer (OS, HR = 1.87, 95% CI = 1.22–2.84, p = 0.0037; disease-specific survival (DSS) HR = 2.07, 95% CI = 1.25–3.43, p = 0.0047)." (PMID 34150844, 2021). "We demonstrate that YAP1 is an independent prognostic marker associated with recurrence and unfavorable survival in pancreatic cancer." (PMID 32054505, 2020). "Subsequently, we explored the biological background of the obtained results with the aim to identify the most significant networks and relationships associated with YAP1 expression in pancreatic cancer." (PMID 32054505, 2020). "Next, we investigated co-transcriptional activity of YAP1 in synthesis of secreted proteins associated with remodeling of the tumor microenvironment in pancreatic cancer." (PMID 32054505, 2020). "Based on the obtained results, we suggest that YAP1 is involved in the transcription of genes associated with remodeling of the pancreatic tumor microenvironment." (PMID 32054505, 2020). "The metastatic properties of YAP1-overexpressing pancreatic cancer cells were examined in immune-deficient NSG mice orthotopically injected with pancreatic cancer cells." (PMID 31575084, 2019). "Yes-associated protein (YAP)-1 is highly upregulated in pancreatic cancer and associated with tumor progression." (PMID 31575084, 2019). "To further examine the role of YAP1 in apoptosis induced by PKCι knockdown in PDAC, we performed the gain/loss-of-function assays of YAP1 in pancreatic cancer cells." (PMID 30214681, 2018). "Further, we found that key nodes of regulation by our confirmed hits in this interaction map were known molecules that modulate survival, EMT and drug resistance in Ras mutated pancreatic cancers, such as YAP1, SIRT1, BAG3, ILK, CDK5, HDACs or GSK3β." (PMID 30325918, 2018). "Furthermore, the influence of GPRC5A on promoting the proliferation and migration of pancreatic cancer cells was partially reversed by YAP1 deficiency in PANC1 cells, which was verified by CCK-8, colony formation, transwell, and wound healing assays." (PMID 36735162, 2023). "The core components of the Hippo signaling pathway, including yes association protein 1 (YAP1), promote the migration, invasion, and malignancy of cancer cells, and inhibiting YAP1 expression suppresses pancreatic cancer progression by disrupting tumor-stroma interaction." (PMID 33648545, 2021). "Moreover, yes-associated protein 1 (YAP1) expression was very recently shown to be crucial for maintenance of the squamous subtype in pancreatic cancer." (PMID 32414223, 2020). "Thus, YAP1 supports pathways activated by mutated K-RAS, and active YAP1 pathway emerged as a putative marker and therapeutic target against pancreatic cancers showing K-RAS independency." (PMID 32708716, 2020). "We found that YAP1 knockdown decreased the growth of KP4 cells on stiff ECMs, suggesting that YAP1 suppressed the growth of pancreatic cancer cells independently of TEAD family proteins." (PMID 40124511, 2025).